NOX3 (NADPH oxidase 3)
Description:
NADPH oxidase that catalyzes the generation of superoxide from molecular oxygen utilizing NADPH as an electron donor, upon formation of a complex with CYBA/p22phox. Plays a role in the biogenesis of otoconia/otolith, which are crystalline structures of the inner ear involved in the perception of gravity (By similarity).
Synonyms: MOX-2; GP91-3
Tractability: Antibody: its Gene Ontology location is reachable by antibodies, with high confidence; UniProt places it where antibodies can reach, with medium confidence; UniProt predicts a signal peptide or a membrane-spanning region. PROTAC: a small molecule that binds it is known.
Target class: Enzyme; Oxidoreductase
Gene: Protein-coding gene on chromosome 6 (155,395,368 to 155,455,839, reverse strand). Ensembl gene ENSG00000074771.
Subcellular location: Cell membrane
Subcellular location (Human Protein Atlas): Vesicles
Pathways (Reactome):
Signal Transduction: RAC1 GTPase cycle; RAC3 GTPase cycle; RHO GTPases Activate NADPH Oxidases
Gene Ontology:
Molecular function: protein binding; superoxide-generating NAD(P)H oxidase activity; superoxide-generating NADPH oxidase activity; heme binding; NAD(P)H oxidase H2O2-forming activity; oxidoreductase activity
Biological process: defense response; superoxide anion generation
Cellular component: extracellular exosome; NADPH oxidase complex; plasma membrane; cytoplasm; membrane
Genetic constraint (gnomAD): Loss-of-function variants: 49 observed, 51.83 expected, observed/expected ratio (o/e) 0.95, 90% interval 0.75 to 1.2. The upper end of that interval is the gene's LOEUF score, 1.2, which puts it in group 5 of 6, group 1 being the genes least tolerant of losing a copy. Missense variants: 558 observed, 571.86 expected, observed/expected ratio (o/e) 0.98, 90% interval 0.91 to 1.05. Synonymous variants: 206 observed, 216.91 expected, observed/expected ratio (o/e) 0.95, 90% interval 0.85 to 1.07.
Homologues: Orthologues: chimpanzee NOX3 (99% identical), macaque NOX3 (96% identical), dog NOX3 (86% identical), pig NOX3 (84% identical), guinea pig NOX3 (83% identical), rabbit NOX3 (83% identical), rat Nox3 (81% identical), mouse Nox3 (81% identical). Paralogues in human: CYBB (59% identical), NOX1 (56% identical), NOX4 (36% identical), DUOX1 (32% identical), DUOX2 (31% identical), NOX5 (30% identical).
Diseases named in the same sentence as NOX3 in open-access papers:
NOX3 is named in the same sentence as 43 diseases in open-access papers, as found by Europe PMC text mining. Sharing a sentence is not in itself a finding about the gene and the disease. The quoted sentences say what the papers report.
hearing loss (9 papers, 2021 to 2025). "This is a ground-breaking study for Nox3-related research, since Mohri and colleagues not only investigated the exact location of Nox3 in the cochlea, but also described its role for different forms of hearing loss, which will be discussed in Section 5.1." (PMID 38397817, 2024). "Mohri and colleagues investigated, besides several other important Nox3-related topics (see Section 2, Section 3 and Section 4), also the role of Nox3 during cisplatin-induced hearing loss." (PMID 38397817, 2024). "The precise kinetics of NOX3 expression and its histological correlates remain therefore to be fully understood in the context of noise-induced hearing loss." (PMID 35273964, 2022). "Together, growing evidence indicates that NOX3 is a common source of ROS in several forms of acquired sensorineural hearing loss, namely noise trauma, cisplatin and age-related hearing loss." (PMID 36188374, 2022). "NOX3 is needed for normal vestibular development but NOX-derived ROS have also been implicated in the pathophysiology of sensorineural hearing loss." (PMID 35273964, 2022). "Based on these findings, an active role of NOX3 in the pathophysiology of noise-induced hearing loss can be demonstrated, in line with recent evidence obtained in other forms of acquired hearing loss." (PMID 35273964, 2022). "In the present study we addressed the role of NOX3 in noise-induced hearing loss by subjecting two different NOX3 deficient mouse strains and their wild type littermates to white noise exposure." (PMID 35273964, 2022). "Counter-intuitively however, one recent report suggests a protective role of NOX3 in noise-induced hearing loss." (PMID 35273964, 2022). "The first study reported a small protective effect of NOX3 against noise-induced hearing loss but solely at a very specific frequency (8 kHz)." (PMID 35273964, 2022). "NOX3 expressed in cochlea produces ROS that has been linked to hearing loss, while NOX3 expressed in the vestibule produces ROS involved in gravity perception." (PMID 34205998, 2021). "In addition, NOX-1 upregulation and NOX-3 downregulation were reported for the cochlea of rats exposed to loud noise in the context of hearing loss." (PMID 36719770, 2023). "Genetic Nox-3 deficiency protects from noise-induced sensorineural hearing loss." (PMID 36719770, 2023). "Mutations in NOX3 were investigated to be involved in noise-related hearing loss via a Genome-Wide Association Study, and the abnormalities in cerebellar structure and function resulting from neuronal precursor cell proliferation induced by ROS in animal models." (PMID 37854190, 2023). "In conclusion, our data demonstrates that NOX3 contributes significantly to noise-induced cochlear damage as previously demonstrated for two other forms of acquired forms of sensorineural hearing loss, namely age-related and cisplatin-induced hearing loss." (PMID 35273964, 2022). "The exclusive and specific expression of NOX3 in the inner ear opens interesting opportunities for pharmacological or molecular interventions aiming at prevention of several acquired forms of hearing loss including noise-induced hearing loss." (PMID 35273964, 2022). "However, in a pathogenic context such as ageing or cisplatin exposure, the NOX3-derived ROS contribute significantly to morphological and functional consequences with destruction of the neurosensory cells in the cochlea and hearing loss." (PMID 35273964, 2022). "Based on these findings, an active role of the ROS generating enzyme NOX3 in the pathophysiology of noise-induced hearing loss can be demonstrated, in line with NOX3 implication in other forms of acquired hearing loss such as age-related hearing loss and cisplatin-induced hearing loss." (PMID 35273964, 2022). "Based on the results previously obtained from NOX3 knockout mice, we hypothesize that mice receiving NOX3 siRNA will be at least partially protected from noise-induced hearing loss." (PMID 36188374, 2022).
hearing loss (continued). "In the absence of pharmacological inhibitors of NOX3, molecular therapies may be of clinical relevance in the near future, as NOX3-deficiency has recently been shown to protect from acquired forms of hearing loss." (PMID 36188374, 2022). "Therefore, clarification of the role of NOX3 in noise-induced hearing loss is needed and our study aims at filling this gap." (PMID 35273964, 2022). "Therefore, the role of NOX3 in the context of noise induced hearing loss remained to be clarified." (PMID 35273964, 2022). "Thus, Nox3 might serve as a molecular target for the development of therapeutics for sensorineural hearing loss, particularly cisplatin-induced, age-related, and noise-induced hearing loss." (PMID 33849947, 2021). "While this study nicely establishes TRPV1 as potential target for therapeutic treatment against cisplatin-induced hearing loss, no in vivo experiments for analysis of Nox3 in this context were performed." (PMID 38397817, 2024). "Unfortunately, like in other previous studies of the Nox3 research field, the group did not clarify the exact interplay of Nox-derived ROS during Ca2+ signaling and the subsequent age-related hearing loss." (PMID 38397817, 2024). "Yet, targeting the enzymatic complex at the origin of pathogenic redox signaling – namely NOX3 – rather than scavenging its product, appears as a promising strategy in acquired hearing loss." (PMID 36188374, 2022). "Although Nox3-expressing cells can serve as prognostic markers for hearing impairment, Nox3 detection remains cumbersome because of a lack of reliable detection methods, barring the ISH-based RNAscope." (PMID 33849947, 2021). "Note also that the similarities of the protective effect of NOX3 deficiency and p22phox deficiency suggest that there is not a major role of other p22phox-dependent NOX isoforms (i.e. NOX1, NOX2, and NOX4) in the pathophysiology of noise induced hearing loss." (PMID 35273964, 2022).
sensorineural hearing loss (5 papers, 2021 to 2025). "The reactive oxygen species (ROS)-generating enzyme NOX3 has recently been implicated in the pathophysiology of several acquired forms of sensorineural hearing loss, including cisplatin-, noise- and age-related hearing loss." (PMID 36188374, 2022). "This corroborates the strong rationale to target NOX3 activity for prevention or treatment of noise-induced and other forms of acquired sensorineural hearing loss." (PMID 35273964, 2022). "Growing evidence suggests that the reactive oxygen species (ROS) generating NADPH oxidase enzyme NOX3 is an important mediator of oxidative damages and a possible common mediator in several forms of sensorineural hearing loss." (PMID 35273964, 2022). "Recently, we reported that Nox3 expression in the cochlea is induced by aging, cisplatin treatment, and intense noise exposure, contributing to the primary source of reactive oxygen species (ROS) and causing acquired sensorineural hearing loss." (PMID 41339603, 2025). "NOX3 activity therefore seems to be a common molecular trigger influencing redox regulated neuronal activity, pathologically altered in different forms of acquired sensorineural hearing loss." (PMID 35273964, 2022). "Therefore, there is a strong rationale in targeting NOX3 activity to protect or promote regeneration of the auditory synapse in order to prevent early stages of acquired sensorineural hearing loss." (PMID 36188374, 2022). "Furthermore, we reported that Nox3 expression in the cochlea is upregulated by aging, cisplatin treatment, and intense noise exposure, contributing to increased ROS production and causing acquired sensorineural hearing loss (SNHL)." (PMID 41339603, 2025).
emphysema (4 papers, 2013 to 2024). "We previously reported that a physiologic consequence of TLR4 deficiency is postdevelopmental, age‐related spontaneous emphysema, and identified increased oxidant production via NADPH oxidase 3, as a potential mechanism in lung Ec." (PMID 30790400, 2019). "Previously, intracellular oxidants such as those derived from the NADPH oxidase (Nox) system have been implicated in disease states, and TLR4 deficiency in mice led to the up-regulation of Nox3 in lungs which correlated with the emphysema phenotype." (PMID 24205107, 2013). "Zhang and colleagues investigated, for the first time, a possible connection between Nox3 and pulmonary emphysema, which is a major contributor to chronic pulmonary diseases in a mouse model." (PMID 38397817, 2024). "Remarkably, studies have shown that TLR4 deficiency in mice led to spontaneous emphysema, without a notable increase in inflammatory cell numbers, while also triggering elevated endogenous Nox3 (NADPH Oxidase 3) activity in endothelial cells." (PMID 37240069, 2023).
Insulin resistance (4 papers, 2018 to 2024). Increased resistance towards insulin, that is, diminished effectiveness of insulin in reducing blood glucose levels. "A follow-up study from the same lab further focused on the role of free fatty acids (FFA) during insulin resistance and the role of Nox3 in this context." (PMID 38397817, 2024). "Their aim was to define the role of NOX3-derived ROS in insulin resistance in diabetic (db/db) mice and HepG2 hepatocytes treated with palmitate." (PMID 35740032, 2022). "Previous studies showed that TNF-α induced the expression of NOX3, promotes ROS production, activates the JNKs signaling pathway, and produces insulin resistance in the HepG2 cells." (PMID 32425786, 2020). "In addition, skimmin also inhibited the increased of NOX3 protein compared with the insulin resistance group induced by palmitic acid." (PMID 32425786, 2020). "This nice publication identified Nox3 as sole ROS source in TNF–stimulated HepG2 cells, the JNK-pathway as ROS-mediated target, the involvement of ROS in cellular insulin resistance and a possible interplay of TNF, PKC and p47phox-mediated activation of Nox3." (PMID 38397817, 2024). "An increase of Nox3 protein expression and JNK1/2 phosphorylation was also detected in white adipose tissue of mice with artificially induced insulin-resistance." (PMID 38397817, 2024). "Previous studies showed that the ROS production increased by up-regulating the expression of NADPH oxidase 3 (NOX3), activating p38MAPK and JNK signaling pathway, and inducing insulin resistance in palmitate-induced HepG2 cells." (PMID 32425786, 2020). "Additionally, Nox3 was shown to be upregulated in conditions of stress induced by TNF-α in HepG2 cells, suggesting a role for Nox3 in insulin resistance in the liver." (PMID 30597847, 2018).
Hypertension (3 papers, 2016 to 2024). The presence of chronic increased pressure in the systemic arterial system. "Nox3 has been associated with diabetic nephropathy and/or renal damage in models of hypertension." (PMID 38671903, 2024). "Two of them, IFNAR1 and NOX3 were previously implicated in pathogenesis of hypertension." (PMID 27980621, 2016). "Adipositas, as well as hypertension, can contribute to cardiovascular diseases and the role of Nox3 in this context will be discussed in Section 5.4." (PMID 38397817, 2024). "It is thought that Nox3 plays a role in the development of renal damage in individuals with diabetes and hypertension; however, further research is needed to understand its precise mechanisms and potential therapeutic targets." (PMID 38671903, 2024). "This analysis allowed us to identify 6 well-annotated genes: RTP4, FXYD6, GDF11, IFNAR1, NOX3, and HLA-DQ2, associated with dynamics of future hypertension incidence." (PMID 27980621, 2016).
auditory neuropathy (2 papers, 2021 to 2022). A hearing disorder characterized by impaired transmission of signals through the auditory nerve, resulting in mild to severe hearing loss and poor speech perception. "Remarkably, p22phox knockout and NOX3 mutant mice were both protected against noise induced auditory synaptopathy and auditory neuropathy, with markedly conserved auditory synapses and neuron integrity." (PMID 35273964, 2022). "However, the auditory neuropathy mechanism induced by Nox3 might be involved in ARHL to some extent because tdTomato-positive SGNs were detected and found to increase with aging." (PMID 33849947, 2021).
breast carcinoma (2 papers, 2022 to 2024). "Nox3 mRNA expression was increased in the murine breast cancer line 4T1 after isolation from an established tumor setting in mice." (PMID 38397817, 2024). "Nox3 mRNA was also detected in the murine breast cancer line 4T1." (PMID 38397817, 2024). "After RISP knock-down in various breast cancer cell lines they detected a decrease in Nox3 mRNA." (PMID 38397817, 2024).
melanoma (2 papers, 2022). A malignant, usually aggressive tumor composed of atypical, neoplastic melanocytes. "And in some cancers, the expression of YY1 is affected by mutations in certain genes; for example, in melanoma, the expression of YY1 is reduced by NOX3 and RTCB mutations." (PMID 35791393, 2022). "In this regard, we showed that 13% of the melanoma patients have alterations on NOX1 gene, 7% on NOX2, NOX3 and NOX5, and 15% on NOX4." (PMID 35326089, 2022). "In melanoma, NADPH oxidase 3 (NOX3) and RNA 2',3'-cyclic phosphate and 5'-OH ligase (RTCB) mutations reduce YY1 expression." (PMID 35791393, 2022).
anaplastic thyroid cancers (1 paper, 2015). "NOX1, NOX3, and NOX5 expression suggested minor changes in thyroid cancers, whereas the expression of NOX2 and NOX4 showed increased mRNA synthesis in papillary thyroid and anaplastic thyroid cancers." (PMID 26664298, 2015).
autoimmune disease (1 paper, 2019). A disorder resulting from loss of function or tissue destruction of an organ or multiple organs, arising from humoral or cellular immune responses of the individual to their own tissue constituents. "Our data implicate monocyte-derived oxidative processes in autoimmune diseases and their treatment, and identify NOX3 genetic variant, monocyte counts and redox state as parameters potentially useful to inform clinical decisions on DMF therapy of RRMS." (PMID 31300673, 2019).
cervical cancer (1 paper, 2019). A primary or metastatic malignant neoplasm involving the cervix. "DUOX1 and DUOX2 were also the most abundant NOX transcripts in cervical cancer patients, whereas NOX3 was the least abundant and was undetectable in normal control subjects." (PMID 31706280, 2019).
demyelinating disease (1 paper, 2016). A broad group of disorders that affect the myelin sheaths that cover the neurons. "Furthermore, NOX3 and NOX5, as inducers of OL differentiation, represent novel targets for therapies of demyelinating diseases, including multiple sclerosis, associated with impairment of OL differentiation." (PMID 27313511, 2016).
diabetic nephropathy (1 paper, 2016). "NOX3 is one of the isoforms of nicotinamide adenine dinucleotide phosphate (NADPH) oxidase, an enzyme-producing reactive oxygen species associated with renal function and a risk of diabetic nephropathy and HTN in Africans." (PMID 27980621, 2016).
hepatocellular carcinoma (1 paper, 2025). A malignant tumor that arises from hepatocytes. "Epicatechin even promotes lower lipid deposition and NOX3/NOX4 expression in a human hepatocellular cancer cell line incubated with palmitate." (PMID 39980683, 2025).
inner ear diseases (1 paper, 2024). "The study described for the first time a possible involvement of Nox3-related inner ear diseases in humans, which started the investigation of Nox3 as harmful ROS source and possible therapeutic target (Section 6) for patients." (PMID 38397817, 2024).
liver diseases (1 paper, 2024). "Insulin treatment increased Nox3 protein levels in HepG2 cells, a commonly used cell line for investigation of liver diseases." (PMID 38397817, 2024). "The human liver cell line HepG2 naturally expresses Nox3 mRNA and protein, which is of critical importance, since this cell line serves as cellular model for most of the Nox3-related research on liver diseases (see Section 5.4.1 and Section 5.4.2)." (PMID 38397817, 2024).
lung diseases (1 paper, 2024). "All of these studies clearly demonstrate a critical involvement for Nox3-mediated ROS production as rather destructive factor during lung diseases." (PMID 38397817, 2024). "The discovery of Nox3 as important player for the progression of lung diseases was furthermore confirmed by a series of genetic screens, which delivered correlative data between the NOX3 gene and different lung diseases." (PMID 38397817, 2024).
Nystagmus (1 paper, 2024). Rhythmic, involuntary oscillations of one or both eyes related to abnormality in fixation, conjugate gaze, or vestibular mechanisms. "Nox3-deficient mice showed no nystagmus in any of these tested positions." (PMID 38397817, 2024). "The group nicely showed that the nystagmus occurrence, usually observed in mice with intact vestibular functions, was absent in Nox3-deficient mice and concluded that a functional otoconial structure is critical for the development of a nystagmus in magnetic fields." (PMID 38397817, 2024).